EGFR (epidermal growth factor receptor)
Diseases named in the same sentence as EGFR in open-access papers (continued):
Sharing a sentence is not in itself a finding about the gene and the disease.
tumor (continued). "Similarly, inhibition of the epidermal growth factor receptor and VEGFR phosphorylation on tumor-associated endothelial cells can produce apoptosis in tumor vasculature and tumor cells of orthotopic human colon carcinoma in nude mice." (PMID 26328524, 2015). "Varella-Garcia extended the EGFR FISH positive criteria to include larger and brighter EGFR signals compared to CEP7 signal in >10 % of tumour tissue with normal size EGFR signal in adjacent non- malignant cells, and recommended that fifty cells should be analysed in four distinct tumour areas." (PMID 26478746, 2015). "In solid tumors, some of the most successful antibodies directly targeting tumor cells are those that block the ErbB family [which include epidermal growth factor receptor (EGFR) and human epidermal growth factor receptor 2 (HER2)] or vascular endothelial growth factor (VEGF)." (PMID 26217587, 2015). "In addition to its potential role in tumor promotion and progression, overexpression of IL-6 has been suggested to promote resistance to EGFR TKIs in both EGFR-dependent and EGFR-independent manners." (PMID 26513016, 2015). "Additional studies are needed to clarify whether tumor cells with extracellular domain-truncated HER2 or with alternative signaling from EGFR could benefit from the mechanism of action of lapatinib." (PMID 25902832, 2015). "Suppression of AREG by ectopic miR-34a expression prevented tumor invasion, and inhibited EGFR, which might be the potential molecular targets for future HNSCC therapy." (PMID 25762634, 2015). "Our study suggests that the combined evaluation of EGFR and Beclin1 autophagic protein expression in tumor tissue sections could add valuable information to the prognostic molecular profile of GB." (PMID 25821789, 2015). "In relation to codon 13, some studies have shown that mutations in this codon could be less aggressive than in codon 12 and that patients with KRAS Gly13Asp mutant tumours could benefit from anti-EGFR therapies." (PMID 24720724, 2014). "Therefore, the expression of EGFR and cMET on single cells grown either as a monolayer or a tumor spheroid using the ULA plating method was determined by flow cytometry from cells cultured in basal media for four days." (PMID 24638075, 2014). "EGFR expression is commonly increased in human cancers, and preclinical evidence suggests a direct impact of EGFR on the sensitivity of tumor cells toward ionizing radiation." (PMID 24141602, 2014). "Other authors found that EGFR-TKI affects the cancer related networks of pro-inflammatory cytokines and activates the lymphocytic responses; this evidence suggests a possible synergism between the EGFR molecular pathway inhibition and immune system modulation in promoting tumor shrinkage." (PMID 25271833, 2014). "In addition, many studies indicate that the TGF-β1 and EGFR signaling pathways are frequently activated during pancreatic carcinogenesis, and they have been shown to be crucial in promoting tumor cell migration and invasion." (PMID 24625091, 2014). "Notably, PHD3-silenced tumour cells exhibited a striking and prolonged increase in EGFR phosphorylation under basal conditions as well as after EGF stimulation for 5 and 15 min." (PMID 25420773, 2014). "Similarly, heregulin levels, evaluated both in plasma and tumor specimens, were found to be significantly higher in patients that relapsed on anti-EGFR therapy." (PMID 24811491, 2014). "As already reported EGFR copy number was variable within the same tumor and may vary according to the architectural pattern." (PMID 24885034, 2014). "The EGFR signals were scored over the range 4.6–56.2, the C/EBPβ signals were scored over the range 17.2–44.2, and the miR-31 signals were scored over the range 12.0–68.4, in the various tumor tissues." (PMID 25229239, 2014).
tumor (continued). "In the present study, the tumor tissue of 10 patients was investigated for mutation status, but no mutations were found and the incidence of EGFR mutations in patients with ESCC was extremely low." (PMID 24944678, 2014). "Monitoring of tumor glucose utilization by [18F]fluorodeoxyglucose (FDG)-positron emission tomography (PET) was implemented for the early prediction of treatment response to EGFR-TKIs in NSCLC." (PMID 24928511, 2014). "Given the implicated role of ACK-1 in EGFR, KRAS and ALK signaling, we suggest a potential therapeutic niche for combination studies with bosutinib selecting for patients with ACK-1 overexpression, specifically in circumventing tumor metastasis and recurrence." (PMID 24461128, 2014). "Collectively, the results of our present study indicate that stilbenoids may affect both EGFR and Stat3 in malignant, EGFR-overexpressing tumor cells." (PMID 25063218, 2014). "Apart from its tumor targeting effect, the EGFR-directed antibody moiety contained within the DbαEGFR-scTRAIL molecule may actively interfere with EGFR function while simultaneously stimulating apoptosis." (PMID 25198428, 2014). "EGFR+ tumour cells showed two distinct clones with varying ploidy (right)." (PMID 24154962, 2014). "We hypothesized that EGFR in EAC promotes an aggressive tumor phenotype and results in poor outcomes and neoadjuvant chemotherapy resistance." (PMID 25216514, 2014). "None of the patients harboring a K-Ras mutant tumor achieved an objective response to erlotinib compared with 10 out of 30 wild-type patients evaluable for the analysis (RR: 0% vs. 33%; p = 0.296): of these 10 K-Ras wild-type patients, 8 harbored an EGFR mutant tumor." (PMID 25300933, 2014). "In addition, because EGFR plays a vital role in the regulation of cell proliferation, survival and differentiation, partial normalization of tumor vessels by bevacizumab could cause proliferation of the tumor cells, which could make them more sensitive to EGFR TKI." (PMID 25344762, 2014). "In addition, KPT-276 exhibited high anti-tumor activity in EGFR-TKI-resistant NSCLC cell xenografts." (PMID 24595136, 2014). "Considering that many multi-kinase inhibitors under development have AXL as one of their targets, further exploration of the pharmacologic inhibition of this pathway in pre-clinical models, including tumor cells lines with resistance to anti-EGFR drugs, should be pursued." (PMID 25193853, 2014). "However, in the present study, we report that despite HLA-DR augmentation on the tumor cells, in some instances EGFR inhibition suppressed antitumor T cell responses by inducing the production of TGF-β and PGE2." (PMID 25240937, 2014). "Our findings demonstrate that the mesenchymal tumor cells are sensitive to dasatinib treatment and that co-treatment of EGFR mutant epithelial lung cancer cells with dasatinib and erlotinib could prevent the emergence of erlotinib resistance." (PMID 25193862, 2014). "Therefore, we conclude that combined inhibition of PI4KIIα and EGFR exerts a multiple anti-tumor effect." (PMID 24801752, 2014). "Pathology, tumor size, tumor disappearance rate, and the EGFR and ALK markers were analyzed." (PMID 24885886, 2014). "KPT-185 also exhibited a strong anti-tumor activity in EGFR-TKI-resistant NSCLC cell lines." (PMID 24595136, 2014). "However, 2 PNET specimens had focal EGFR amplification, with only 5–10% of tumor cells identified as positive." (PMID 24986561, 2014). "Numerous phase III studies have shown that EGFR TKIs such as gefitinib or erlotinib have strong anti-tumor activity and increase survival in patients with NSCLC harboring activating EGFR mutation not only in second and third line, but also in first line and maintenance treatment." (PMID 24836053, 2014). "We then examined whether administration of the EGFR inhibitor altered tumor cytokine profiles and expression of immune-related molecules on tumor cells." (PMID 25240937, 2014).
tumor (continued). "EGFR is overexpressed or mutated in most NSCLC cases, and deregulated expression of EGFR together with ligand binding and concomitant receptor activation promotes tumor cell growth, proliferation, and survival." (PMID 25413624, 2014). "Tumours with mutated Ras neither show progression-free survival nor benefit from anti-EGFR tyrosine kinase inhibitors (TKIs) or monoclonal antibodies (MAbs)." (PMID 25228915, 2014). "Taken together, these findings suggest that TCTP enabled the HeLa cells to acquire chemoresistance in etoposide-induced apoptosis possibly through inhibition of initiator or effector caspase activity thereby preserving the key players for tumor cell function such as EGFR and PLC-γ." (PMID 24606760, 2014). "Six out of the 12 patients whose tumor expressed EGFRvIII responded to EGFR inhibitors (p = 0.003)." (PMID 24352766, 2014). "In addition, it significantly enhanced AG1478-induced inhibition of tumor cell survival and strengthened the effect of the EGFR-targeting anti-cancer drug Iressa in xenograft tumor models." (PMID 24801752, 2014). "Because microRNAs are naturally existing small molecules and target multiple genes, overexpression of miR-608 or miR-34a could exert greater anti-tumor effects than EGFR or MET inhibitions." (PMID 24621885, 2014). "This is particularly relevant when the tumor is not easily accessible for biologic sample collection and thus oncologists need to spare tissue for fundamental analyses, such as EGFR mutations and EML4-ALK translocation." (PMID 25300933, 2014). "EGFR staining was present in the tumor cell cytoplasm from every dog." (PMID 24423144, 2014). "Finally, in relation to the immunoexpression of the protein EGFR,direct correlations with the serum levels of the tumor markers CEA (p=0.004) and CA19.9 (p=0.016), and with T staging (p=0.016) and N staging (p=0.029), wereobserved." (PMID 25004291, 2014). "Targeting the IGF1R pathway may be a promising strategy for overcoming gefitinib resistance in EGFR mutation-positive NSCLC induced by lung CSCs and microenvironment factors such as tumor hypoxia." (PMID 24489728, 2014). "Similarly, the tumor suppressor gene PTEN regulates negatively the P13K/ATK pathway acting as a downstream effector of EGFR." (PMID 25272957, 2014). "•EGFR traffic promoted by antineoplastic therapy is important in tumor resistance." (PMID 24295852, 2014). "To address this issue, we analysed 12 cases with established EGFR mutation status for therapeutic purposes (each 6 cases with/without EGFR mutations) and evaluated the tumor specimens for hamartin, p-tuberin and p-mTOR expression." (PMID 24593867, 2014). "EGFR or HER2-mediated stimulation of cell proliferation and survival pathways can cause cancer cells to become dependent on these pathways, or “addicted,” to EGFR or HER2 expression to maintain tumor growth and survival." (PMID 25566499, 2014). "Similarly, a more recent study found that mutant KRAS shRNA-knockdown in NSCLC suppresses tumor growth also sensitizing tumor cells to p38 and EGFR inhibitors." (PMID 25593996, 2014). "This may be due to the heterogeneous nature of BBCs in which not only the expression of EGFR is variable but also the activity of EGFR and dependence of the tumor on that activity." (PMID 25361177, 2014). "Since the inactivation of both EGFR and C/EBPβ can also be seen in tumor cells (arrows), this further supports the hypothesis that there is a concordance between the activation of EGFR and the activation of C/EBPβ." (PMID 25229239, 2014). "Metformin in combination with dasatinib further activated AMPK and induced EGFR degradation as well as apoptosis, implicating that induction of metabolic stress could mediate anti-tumor effect and serve as an anti-cancer strategy." (PMID 24457597, 2014). "In addition to EGFR, others have raised the possibility of personalized peptide vaccines or even individualized whole tumor vaccines as more targeted alternatives for immunotherapy." (PMID 25268164, 2014).
tumor (continued). "The possibility to target multiple relevant cell types within the same tumor might compensate for the relatively low overexpression on malignant cancer cells compared with other tumor markers, like EGFR, Her2/Neu or EpCAM." (PMID 24742002, 2014). "We retrospectively investigated 6 cases of this very rare neoplasm in order to investigate the mutational status of KRAS, EGFR, PDGFR-α and KIT, as well as the immunohistochemical expression pattern of CD117, EGFR and COX-2, and possibly find new therapeutic targets." (PMID 24934485, 2014). "Patients were planned to receive first-line platinum-based chemotherapy (CT) and a salvage treatment with anti-EGFR tyrosine-kinase inhibitors (TKIs) was proposed irrespective of tumor mutational status." (PMID 25300933, 2014). "In these studies we proposed that EGFR inhibitors might be effective adjuncts for cancer immunotherapy because these drugs increased MHC-II expression levels on tumor cells, which should enhance CD4+ T cell recognition." (PMID 25240937, 2014). "A link between ACSVL3 and cancer stem cell phenotype was further established by the findings that ACSVL3 expression was regulated by receptor tyrosine kinase pathways that support GBM stem cell self-renewal and tumor initiation, including EGFR and HGF/c-Met pathways." (PMID 24893952, 2014). "We confirmed the expression of COX-2, EGFR, and p65 in this primary tumor by IHC." (PMID 24964787, 2014). "Moreover, the authors showed that plasma fractions enriched in MPs presented an increased amount of focal adhesion kinase (FAK) and epidermal growth factor receptor (EGFR) foretelling different contents of MPs between the different stages of the tumor." (PMID 24424657, 2014). "For example, based on the important roles of NeuGc GM3 and the EGFR for tumor cell immune evasion and proliferation, a combination therapy targeting both molecules may provide a rationale for fighting tumor cells." (PMID 25101077, 2014). "Furthermore, tumor cells exposed to reversible or irreversible EGFR TKIs display early resistance dependent on MET-independent activation of BCL-2/BCL-XL survival signaling." (PMID 25364578, 2014). "Dimerization of EGFR may result in cancer cell proliferation, inhibition of apoptosis, invasion, metastasis, and tumor induced neovascularization." (PMID 24999473, 2014). "In addition, a significantly higher number of tumours in the left colon were found to co-express EGFR/HER-2/HER-4 (P = 0.036)." (PMID 24609222, 2014). "Present in vitro data point to a new, unpredictable effect on tumor cells of AvidinOX-anchored bCet and bPan that, despite engaging two distinct receptor epitopes, both prevent homo and heterodimerization and induce massive lysosomal degradation of EGFR." (PMID 25238453, 2014). "The study showed that, among the 5 tumor samples collected at the time of XL647 failure, only one harbored the T790M mutation and that three patients treated with second line erlotinib derived additional long-term benefit from the EGFR TKI." (PMID 25505694, 2014). "We demonstrated here that the status of predictive anti-EGFR markers may change in tumor genomes of patients with metastatic CRC." (PMID 24676216, 2014). "Furthermore, aberrant expression of β3 integrin is strongly related to epithelial-mesenchymal transition, a process involved in several aspects of tumor metastasis, generation of a stem-like state and resistance to EGFR-targeted therapies." (PMID 25255930, 2014). "PCR-based DNA sequencing analysis of the patient’s tumor specimen revealed no EGFR, BRAF, KRAS, NRAS, PI3KCa, or c-kit mutations." (PMID 25126591, 2014). "In addition to EGFR, Fascin is also recognized as a therapeutic target, as binding with migrastatin analogues inhibits Fascin activity and blocks tumor metastasis." (PMID 25153136, 2014).
tumor (continued). "We subsequently found that culturing human GBM tumor cells on progressively stiffer culture substrates both dramatically increases proliferation and facilitates passage through the G1/S checkpoint of the cell cycle, consistent with an EGFR-dependent process." (PMID 25000176, 2014). "The drug demonstrated anti-tumor activity in EGFR-mutant xenografts at a low dose level." (PMID 25563355, 2014). "Correlations between EGFR mutation-positive status and clinical characteristics have been reported, however, with the mutations being more common in the tumours of never-smokers and females, and in adenocarcinomas." (PMID 25100284, 2014). "In summary, these results may shed light on the different mechanisms of resistance to anti-EGFR treatment in solid tumors experiencing high cell-cell contact vs. metastatic and circulating tumor cells experiencing minimal cell-cell contact." (PMID 25272226, 2014). "EGFR-TKIs inhibit TK self-phosphorylation by competing with adenosine triphosphate for the binding sites of the TK domain, thereby blocking the transmission of downstream signaling and inhibiting tumor cell proliferation." (PMID 24527096, 2014). "To overcome this problem, we and other groups have recently proposed that the increase of MHC class II protein expression on tumor cells obtained with EGFR inhibitors could be implemented to enhance HTL anti-tumor responses." (PMID 25240937, 2014). "The ability of tumor cells to repair DNA damage is reduced following EGFR blockade with Cetuximab, and recently it has been demonstrated that the combination of EGFR inhibition and DNA damage-induced therapy increases in vitro and in vivo response of human tumor cells." (PMID 25409711, 2014). "Further clinical trials with third-generation EGFR-TKIs will demonstrate the anti-tumor activities." (PMID 25563355, 2014). "EGFR mutations have been characterized best in NSCLC, where they represent early genetic events in cancer development, which are of fundamental relevance for the biology of these tumours." (PMID 24643470, 2014). "Although we could show the increase of PGE2 production by EGFR inhibition only in tumor cell Sa-3, we believe our result may partly elucidate the mechanism of positive effects of COX-2 inhibitor with erlotinib." (PMID 25240937, 2014). "We propose the use of NTS/NTSR1 tumor expression, as a biomarker for the use of EGFR tyrosine kinase inhibitors in patients lacking EGFR mutation." (PMID 25249545, 2014). "Here we test the hypothesis that microenvironmental stiffness regulates cell cycle progression and proliferation in GBM tumor cells by altering EGFR-dependent signaling." (PMID 25000176, 2014). "PSA values at diagnosis (P = 0.009), Gleason score (P<0.001), clinical tumor stage (P = 0.011), distant metastasis (P = 0.006), Ki-67 LI (P = 0.002), EGFR amplification (P = 0.023), and HER2 amplification (P = 0.001) were also significantly related to cancer-related survival in univariate analysis." (PMID 24516518, 2014). "Thus, the COX-2/PGE2 pathway is partially responsible for immunosuppressive effects of tumor cells through EGFR blockade." (PMID 25240937, 2014). "Scoring with method (C) features more EGFR-positive tumor samples in ADC than in SCC." (PMID 25227424, 2014). "Thus, inhibition of cell migration by the EGFR and cMET inhibitors is partially due to their anti-proliferative effects on tumor cells." (PMID 24638075, 2014). "EGFR is known to be an important anti-tumor target for NSCLC treatment." (PMID 24801752, 2014). "This poses the question as to whether EGFR activation and downstream activation of C/EBPβ co-exist in tumor cells." (PMID 25229239, 2014). "In addition, there was a significant association between the co-expression of EGFR and HER-4 at above 5% or above 10% of tumour cells and poorer disease-free survival (P = 0.019)." (PMID 24609222, 2014).